TRANK1 (tetratricopeptide repeat and ankyrin repeat containing 1)
Synonyms: KIAA0342; LBA1
Tractability: PROTAC: ubiquitination databases record sites on it; its protein half-life has been measured.
Gene: Protein-coding gene on chromosome 3 (36,826,817 to 36,945,057, reverse strand). Ensembl gene ENSG00000168016.
Subcellular location (Human Protein Atlas): Nucleoplasm; Cytosol
Genetic constraint (gnomAD): Loss-of-function variants: 181 observed, 258.35 expected, observed/expected ratio (o/e) 0.7, 90% interval 0.62 to 0.79. The upper end of that interval is the gene's LOEUF score, 0.79, which puts it in group 3 of 6, group 1 being the genes least tolerant of losing a copy. Missense variants: 3,251 observed, 3,708.6 expected, observed/expected ratio (o/e) 0.88, 90% interval 0.85 to 0.9. Synonymous variants: 1,360 observed, 1,415.7 expected, observed/expected ratio (o/e) 0.96, 90% interval 0.92 to 1.
Homologues: Orthologues: macaque TRANK1 (98% identical), chimpanzee TRANK1 (98% identical), dog TRANK1 (87% identical), guinea pig TRANK1 (85% identical), pig TRANK1 (83% identical), mouse Trank1 (81% identical), rat Trank1 (81% identical), rabbit TRANK1 (78% identical), tropical clawed frog trank1 (47% identical), Drosophila melanogaster CG31038 (3% identical), Drosophila melanogaster lmgB (2% identical). Paralogues in human: FAM89B (2% identical), FAM89A (2% identical).
Diseases named in the same sentence as TRANK1 in open-access papers:
TRANK1 is named in the same sentence as 23 diseases in open-access papers, as found by Europe PMC text mining. Sharing a sentence is not in itself a finding about the gene and the disease. The quoted sentences say what the papers report.
schizophrenia (12 papers, 2013 to 2025). A major psychotic disorder characterized by abnormalities in the perception or expression of reality. "TRANK1 demonstrated a strong association in schizophrenia that has been previously documented as a BD risk gene." (PMID 34502224, 2021). "Previously, TRANK1 has been cited as a robust risk locus for both schizophrenia (SZ)." (PMID 37198259, 2023). "CNTNAP2 has previously been linked to autism and intellectual disability, BRAF to epilepsy, TRANK1 to schizophrenia, and LRPPRC/MYO7A to mitochondrial and ciliary disorders." (PMID 40282380, 2025). "In schizophrenia, both CACNA1C and ANK3 were identified, and in bipolar disorder TRANK1 and CACNB2 were also significantly associated." (PMID 23637625, 2013). "A worldwide case-control GWAS in 673 KLS cases and ethnically matched 15,341 controls found a strong significant association within the 3′region of the Tetratricopeptide Repeat And Ankyrin Repeat Containing 1 (TRANK1) gene locus, previously associated with bipolar disorder and schizophrenia." (PMID 34679324, 2021). "Several of these genomic markers are shared between BD and schizophrenia such as CACNA1C, CACNB2, NCAN, TRANK1, ITIH3-ITIH4, and ANK3." (PMID 34502224, 2021). "First, although we found that circulating TRANK1 mRNA level was elevated in patients with BD depression, no patients with manic episodes or other major psychiatric disorders, such as schizophrenia and MDD, were included in this study." (PMID 34992606, 2021). "In addition, high levels of anti-TRANK1 (thioredoxin peroxidase-related activator of NF-κB and c-Jun N-terminal kinase) IgG were demonstrated in FEP patients, which could probably serve as a biomarker for identifying patients with schizophrenia." (PMID 39596417, 2024).
bipolar disorder (10 papers, 2013 to 2024). A disorder of the brain that causes unusual shifts in mood, energy, activity levels and the ability to carry out day-to-day tasks. "Tetratricopeptide repeat and ankyrin repeat containing 1 (TRANK1) is a robust risk gene of bipolar disorder (BD)." (PMID 34992606, 2021). "Moreover, Rbfox1, one of the plasticity genes identified in the enrichment analyses is also linked to risk for ASDs, TRANK1 is a susceptibility gene for bipolar disorder, and RIMS1 was identified in a PTSD TWAS." (PMID 38263132, 2024). "Dlgap1, Trank1, and Tafa5 are established risk genes for neuropsychiatric diseases, with Dlgap1 specifically related to major depressive disorder, Trank1 associated with bipolar disorder, and Tafa5 linked to depressive-like behaviors." (PMID 39272155, 2024). "It is notable that TRANK1, one of the most robust bipolar disorder risk genes, showed significant upregulation in AP1AR-DTOE mouse brain and in bipolar disorder cerebral organoids." (PMID 39558356, 2024). "As previously reported, the GMs of patients with bipolar disorder depression were sufficient to induce depression-like behavior in mice, which was attributed to the elevated expression of tetratricopeptide repeat and ankyrin repeat containing 1 (TRANK1), a robust risk gene of bipolar disorder." (PMID 37375029, 2023).
major depressive disorder (4 papers, 2021 to 2024). An episode of depression lasting two or more weeks without an intervening episode of mania. "Compared to HCs, patients with BD depression showed an elevated level of TRANK1 mRNA in peripheral blood (P = 0.002)." (PMID 34992606, 2021).
depression (3 papers, 2021 to 2023). "Gene-trait association was mostly seen with SCZ, additionally, TRANK1, ADD3 and CDAN1 were TWAS positive for BD, OSBPL3 for depressive disorder and CACNA1G for ADHD." (PMID 38104115, 2023).
Anxiety (2 papers, 2024). Intense feelings of nervousness, tension, or panic often arise in response to interpersonal stresses. "On the other hand, despite the biological function of Trank1 in the brain remaining unknown, it is suggested to be involved in immune-related signal regulation, synaptic plasticity, and axon guidance, and its depletion is associated with anxiety-like behavior." (PMID 39594659, 2024).
psychosis (2 papers, 2019 to 2021). "In a rat model of psychosis, one-week social isolation led to increased mRNA expression of TRANK1 in the prefrontal cortex and other specific genes involved in neuroinflammation, formation and integrity of the BBB, and cerebral blood vessel morphogenesis." (PMID 34992606, 2021).
emotional instability (1 paper, 2018). "Particularly, valproic acid, a treatment of mania, has been demonstrated to increase TRANK1 mRNA expression, suggesting a relevance of this gene to emotional instability." (PMID 29545739, 2018).
injury (1 paper, 2021). Damage inflicted on the body as the direct or indirect result of an external force, with or without disruption of structural continuity. "This study also showed that variants in the TRANK1 gene region may predispose to KLS in participants with a difficult birth, suggesting that the TRANK1 gene region modulates newborns’ response to brain injury, resulting in mental and neurological health consequences." (PMID 34679324, 2021).
mood disturbances (1 paper, 2018). "Meanwhile, TRANK1 also confers SZ risk in PGC SZ GWAS and mood disturbances are common in SZ." (PMID 29545739, 2018).
uterine infection (1 paper, 2022). "With such little information known regarding TRANK1 and its role in the bovine endometrium, further investigation is required before a mechanistic link between fertility and uterine infection can be hypothesized." (PMID 35358206, 2022). "This suggests that endometrial TRANK1 expression could play a role in uterine infection related subfertility and one could speculate that reduced TRANK1 expression, mediated by bacterial infection, does not permit the establish of pregnancy." (PMID 35358206, 2022). "A total of 12 pregnancy regulated genes were upregulated only in healthy cows and not cows after uterine infection, including CXCL10, ISG15 and TRANK1." (PMID 35358206, 2022).
infection (3 papers, 2011 to 2025). The state of being infected such as from the introduction of a foreign agent such as serum, vaccine, antigenic substance or organism. "We found a significant temporal induction of ISGs (for example, MX1, RTP4, IRF7, USP18, TRANK1) in alvORG at day 3 after infection compared to mock-infected samples or nasalALI at day 5 and day 7 compared to day 1 after infection." (PMID 40399606, 2025).
psychiatric disorder (3 papers, 2013 to 2024). A disorder characterized by behavioral and/or psychological abnormalities, often accompanied by physical symptoms. "We identified 7 genes (Cap2, Shc3, Lrrc7, Rims2, Cntnap2, Tcf20, and Trank1) associated with neurodevelopmental and psychiatric disorders that feature social impairments." (PMID 38263132, 2024). "Therefore, further investigations on the interactome of TRANK1 with other genetic and environmental factors relevant to BD help to uncover the pathogenesis of this intractable psychiatric disorder." (PMID 34992606, 2021).
neurological disorders (1 paper, 2022). "The function of TRANK1 has been best described in the brain for its role in neurological disorders, and both female and male homozygous Trank1 knock-out mice are reported to be fertile." (PMID 35358206, 2022).
TRANK1 also shares sentences with these, for which no sentence is quoted: autism (1 paper); bacterial infection (1); epilepsy (1); hepatitis C virus infection (1); idiopathic pulmonary fibrosis (1); Intellectual disability (1); Kohlschutter-Tonz syndrome (1); manic episodes (1); mental disorder (1); preeclampsia (1).